SMIM36 (small integral membrane protein 36)
Gene: Protein-coding gene on chromosome 17 (55,449,856 to 55,511,452, reverse strand). Ensembl gene ENSG00000261873.
Subcellular location: Membrane
Gene Ontology:
Cellular component: membrane
Homologues: Orthologues: chimpanzee SMIM36 (100% identical), dog SMIM36 (85% identical), rabbit SMIM36 (84% identical), guinea pig SMIM36 (81% identical), rat Smim36 (81% identical), pig SMIM36 (77% identical), zebrafish SMIM36 (61% identical).